S100A8 (S100 calcium binding protein A8)
Diseases named in the same sentence as S100A8 in open-access papers (continued):
Sharing a sentence is not in itself a finding about the gene and the disease.
cancer (continued). "The abnormal expression of S100A8 and unresponsive inflammation can lead to the occurrence of cancer, however, the mechanism of inflammation developing into CRC is still not completely clear." (PMID 37124724, 2023). "LIPUS therapy prevents DOX‐induced cardiotoxicity through inhibition of S100a8/a9‐mediated neutrophil recruitment to the heart, suggesting its potential application in cancer patients undergoing chemotherapy with DOX." (PMID 38023700, 2023). "A small portion of cancer-induced S100A8/A9-producing neutrophils and a large portion of FBR-induced N1 neutrophils endow the synthetic MNs with the capability to recruit TCs from the circulation while suppressing their proliferation." (PMID 37553342, 2023). "Retrieving the immune-TME and TNBC aggression-associated marker genes from the Pan-cancer TCGA-dataset, we found a high positive correlation of the expression of S100A9 and S100A8, two immune suppression marker genes, with AURKA and EZH2 in the TNBC samples." (PMID 37189841, 2023). "Initially, we thought that S100A8 mainly plays a role in premetastatic niche formation, but it has been reported that various types of cancer cells also express TLR4 at the cell surface." (PMID 36932197, 2023). "Conversely, the endogenous lungs of mice with 4T1 cancer were dominated by S100A8/A9 signals and N2 neutrophils, creating an immunosuppressive environment favorable for metastatic outgrowth." (PMID 37553342, 2023). "Initially, we thought that S100A8 would mainly play a role in premetastatic niche formation, but it has been reported that various types of cancer cells also by themselves express TLR4 at the cell surface." (PMID 35780158, 2022). "In this study, we identified HRG as a novel plasma protein that binds directly to and inhibits the heterodimer S100A8/A9, effectively preventing S100A8/A9-mediated organotropic cancer metastasis." (PMID 36142212, 2022). "Initially, we thought that S100A8 mainly would play a role in premetastatic niche formation, but it has been reported that various types of cancer cells also by themselves express TLR4 at the cell surface." (PMID 35780158, 2022). "Both cancer and inflammatory conditions can induce S100A8 upregulation in other cell types than neutrophils, potentially interfering as targets for dimerizer treatment." (PMID 35954190, 2022). "In support of this, we found decreased MDSC numbers, and increased numbers of CD4+ T cells and natural killer T (NK-T) cells in lungs from cancer-bearing mice treated with S100A8." (PMID 35655772, 2022). "Considering the clinical data showing a reciprocal relationship between HRG and S100A8/A9, their balance in cancer patients is one of the few potent determinants of a shift in cancer metastasis to a highly aggressive state." (PMID 36142212, 2022). "We calculated the coefficient of S100A8 expression and immune infiltration level to determine their relationship with the degree of immune infiltration in diverse cancers." (PMID 35646116, 2022). "The linkages between S100A8 and TME, as well as its association with immunological processes/elements and the major histocompatibility complex, were explored to effectively understand the role of S100A8 in cancer immunotherapy." (PMID 35646116, 2022). "This study was aimed at thoroughly examining S100A8 expression in 33 different malignant tumors and determining its potential effect on immune TME." (PMID 35646116, 2022). "Unexpectedly, inhalation of S100A8 shortly after implantation of cancer cells into the lungs delayed cancer growth, leading to increased survival." (PMID 35655772, 2022). "We discovered that several potential cancer stem cell populations highly express most of the SC genes in TN BrCs and confirmed S100A8 and A9 overexpression in a HER2-overexpressing BrC cell line." (PMID 35633393, 2022). "In conclusion, our findings revealed a close relationship and prognostic significance of S100A8 expression in various human cancers." (PMID 35646116, 2022).
cancer (continued). "Somewhat surprisingly, NK cell numbers were reduced in lungs from mice with orthotopic LLC cancers treated with S100A8." (PMID 35655772, 2022). "S100A8 treatment abolished the elevated nitrite levels found in BALF from mice with LLC cancers (1.5 ± 0.3 μM to 0.8 ± 0.1 μM, p < 0.05), although iNOS mRNA did not significantly change regardless of the treatment." (PMID 35655772, 2022). "The massive release of S100A8/A9 from these sources will induce the elevation of plasma levels of S100A8/A9, resulting in the initiation of inflammatory responses as a damage-associated molecular pattern (DAMP) and the modulation of cancer metastasis." (PMID 36142212, 2022). "Of the immunoregulatory genes downregulated by S100A8 in lungs with LLC cancers on Day 10, most were cytokines." (PMID 35655772, 2022). "S100A8+S100A9+CD15+ PeCa specimens were in tendency rather invasive growing cancers (TMA TC odds ratio = 2.872, TMA IF odds ratio = 3.048) and significantly enriched in the HPV+ group of metastasizing PeCa (odds ratio = 8.444, p = 0.0232)." (PMID 36303837, 2022). "In contrast, the S100A8/A9 complex was reported to have anti-cancer activity by increasing natural killer (NK) cell numbers and activity in pancreatic and colon cancer cells transplanted into mice." (PMID 35655772, 2022). "Although S100A8 has been studied in various cancers, its biological function in cancer remains contradictory and poorly understood." (PMID 35646116, 2022). "In conclusion, our results indicate that HRG plays crucial roles in inhibiting cancer growth and metastasis through its absorptive binding with extracellular S100A8/A9." (PMID 36142212, 2022). "Altered S100A8/A9 expression has also been found in different cancer types, including gastric, colorectal, breast, lung, prostate and liver cancer." (PMID 35543413, 2022). "It has been reported that microglia and astrocytes are potential sources of S100A8/A9 secretory production in the brain of cancer-bearing animals." (PMID 36142212, 2022). "In contrast, conditioned media and cytokines derived from cancer cells upregulated the expression of S100A8 and S100A9 in monocytes." (PMID 35651786, 2022). "These myeloid cells produce S100A8, which enhances cancer cell survival and triggers metastatic seeding." (PMID 36241629, 2022). "The S100A8 expression was evaluated in tumors and normal tissues nearby to determine its relationship with cancer." (PMID 35646116, 2022). "Seven upregulated genes (≥2.0-fold), Ccl24 (4.8-fold), Ccl17 (3.9-fold), S100a8 (2.9-fold), Tarm1 (2.7-fold), Anxa10 (2.4-fold), Ptgs2 (2.0-fold), and Ccl22 (2.0-fold) were detected as inflammatory and cancer-promoting genes." (PMID 34948416, 2021). "Taken together, these data suggest S100A8/A9 is upregulated in the premetastatic lung and there is an emerging role of S100A8/A9 to lung metastatic progression/invasion and cancer growth, signaling via known or newly discovered sensing receptors." (PMID 33567747, 2021). "The up-regulation of S100A8/A9 in mammary myoepithelial cells adjacent to the cancer cells was also observed in the 4T1 syngeneic mouse model tumors." (PMID 33446797, 2021). "Another therapeutic option in cancer is targeting the ability of NETs to secrete the Ca2+-binding proteins S100A8 and S100A9." (PMID 34503307, 2021). "S100A8/S100A9 is often upregulated in cancer and is involved in inducing a pro-inflammatory response." (PMID 33469045, 2021). "Several studies strongly suggest that S100A8 is expressed by cancer cells as well as by infiltrating immune and myeloid cells." (PMID 34072157, 2021). "An inflammatory microenvironment, which mainly includes S100A8/9 (calprotectin), promotes cancer metastasis." (PMID 33288848, 2020). "S100A8/9 and CXCL1/2, or S100A7/8/9 and IRAK1, form a feedback loop to cause cancer chemoresistance and drive breast cancer tumor sphere growth." (PMID 32547883, 2020).
cancer (continued). "Prior to this study, S100A8 has been reported to promote autophagy in cancer cells through the cross-talk between mitochondria and lysosomes via ROS, or through the activation of the autophagy initiation complex BECN1-PI3KC343–45." (PMID 32811814, 2020). "Most importantly, the present data regarding the prognostic power of the S100A8/CRP ratio seem to suggest a beneficial role of activated neutrophils for cancer patients." (PMID 32098278, 2020). "The lung senses distant cancer cells and then secretes an abundant amount of S100A8/A9, which in turn attracts distant cancer cells through their surface TLR4." (PMID 32490214, 2020). "Based on recent evidence, S100A8/9 can influence cancer cell growth and proliferation through the apoptotic pathway in a dose-dependent manner mediating the MAPK and NF-κB signaling pathways." (PMID 31528166, 2019). "Because suspension and dense culture leads to cell apoptosis, even for cancer cells, we next explore the function of S100A8/S100A9 in suspended and dense SCC cells." (PMID 31208368, 2019). "S100A8/S100A9 expression in epithelial cancer cells causes enhanced infiltration of immune cells, especially neutrophils, and stimulates settlement of the cancer cells in the lung." (PMID 31208368, 2019). "It has been shown that MDSC migrate along a gradient of the pro-inflammatory S100A8/9 in cancer models." (PMID 31849951, 2019). "Among these genes, S100A8 and S100A9 have been identified as novel diagnostic markers of human cancer." (PMID 31480483, 2019). "Although the aberrant expressions of S100A8/S100A9 has reported in a variety of cancer tissues, the functional studies are also necessary to pay more attention." (PMID 31208368, 2019). "Currently, S100A8/A9 has been found to play an important role in many diseases, such as inflammation, cancer, and can even be used as a typical or atypical marker to diagnose diseases or predict the progress of diseases." (PMID 29942307, 2018). "This is likely a result of colorectal metastatic disease, as S100A8/S100A9 is an important mediator in cancer pathology which induces growth and stimulates metastasis." (PMID 29675023, 2018). "Our results revealed that S100A8 was expressed in cancer cells and that the average number of S100A8-positive cancer cells in tissues from patients with relapse was much higher than that in tissues from patients without relapse." (PMID 30456203, 2018). "We selected 30 cases with para-carcinoma tissue from the 140 samples at random to determine the expression of S100A8 at the protein level in a control group." (PMID 30456203, 2018). "For example, over-expression of CXCL1 and CXCL2 favors cancer cell survival in metastatic sites through the induction of S100A8 and S100A9 secretion from CD11b+Gr1+cells." (PMID 28429725, 2017). "The use of S100A8/A9 as a clinical marker for cancer immune modulation and translation into specific imaging approach will depend in part on further development of the tracer." (PMID 28744322, 2017). "Other than conferring selective sensitivity to drugs which target mediators of S100A8, the knockdown of S100A8 expression with siRNA or shRNA also showed reduced invasinesss and migration of cancer cells." (PMID 28183295, 2017). "We recently established target-specific in vivo S100A8/A9 optical imaging for monitoring of monocyte activity in local inflammation 14 and primary cancer lesions 15, using fluorescence-labeled antibodies." (PMID 28744322, 2017). "While the roles of s100a8/a9 in mucosal healing have been largely overlooked, s100a8 and s100a9 can promote dermal fibroblast proliferation and can facilitate migration of cancer cells via direct and indirect mechanisms." (PMID 28769105, 2017). "In a breast cancer model, CXCL1/2 is produced by cancer cells and serves as a chemoattractant for myeloid cells that are recruited to the lungs, where they produce S100A8/9 to enhance cancer cell survival at the metastatic site." (PMID 28210073, 2017).
cancer (continued). "S100A8 is a member of the S100 multigene family of cytoplasmic EF-hand Ca2 + -binding proteins and was found overexpressed in various cancer types, and is involved in regulating cell proliferation, metastasis and apoptosis." (PMID 28183295, 2017). "In this study, we report that monocytes/macrophages induce S100a8 and S100a9 messenger RNA (mRNA) expression in cancer cells in an extracellular signal-related kinase (ERK)-dependent manner." (PMID 27086923, 2016). "In both cancer cell lines, S100a8 mRNA levels were reduced at 4 h and remained low for 24 h after ERK inhibition." (PMID 27086923, 2016). "In tissue culture and in the liver colonies derived from cancer cells with knockdown of S100A8 and S100A9, MMP2 and MMP9 expression was decreased, consistent with the reduction in migration and invasion." (PMID 27086923, 2016). "Granulocytes did not provoke ERK activation to the same extent, consistent with their reduced ability to induce S100a8 and S100a9 expression in cancer cells." (PMID 27086923, 2016). "We have previously reported that S100A8/A9 suppresses carcinoma growth in vitro by signaling cell cycle arrest at the G2/M checkpoint." (PMID 26883112, 2016). "We have previously reported that expression of intracellular S100A8/A9 in carcinoma cells appears to activate protein phosphatase 2A (PP2A) and restore the cell cycle checkpoint at G2/M, suppressing growth and colony formation in soft agar." (PMID 26883112, 2016). "Based on our in vitro, ex vivo, and in silico findings, we expected that the malignant and metastatic potential of carcinoma cells would be attenuated when S100A8/A9 is increased in vivo." (PMID 26883112, 2016). "We previously reported that ectopic S100A8/A9 expression inhibits cell cycle progression in carcinoma cells." (PMID 26883112, 2016). "This is an important distinction, as S100A8/A9 and IL-17 are known from multiple studies to be critical for the induction of immature myeloid cells in cancer." (PMID 26460825, 2015). "S100A8 gained importance as target for anticancer drug development due to its central role in mediating inflammatory pathways that facilitate cancer metastasis." (PMID 25789858, 2015). "Previous studies have implied that S100A8 and S100A9 have a pathogenic effect in cancer progression in a concentration-dependent manner." (PMID 25673070, 2015). "Despite showing the elevated expression and distinct role of S100A8 in different cancer types, less is known about the expression status or role of S100A8 in KC progression." (PMID 25789858, 2015). "Proinflammatory molecules such as IL-17, CCL20, S100A8, S100A9, and S100A8/A9 have been shown to be implicated in many types of cancer." (PMID 26273651, 2015). "Abnormal expressions of S100A8 proteins were observed in a variety of cancers, such as gastric, lung, breast, liver, pancreatic and squamous esophageal carcinomas." (PMID 25789858, 2015). "S100A8/A9, NT-S100A8 are overexpressed in PDAC stroma when cancer cells express Smad4, suggesting that they are linked with TGFβ1 signalling." (PMID 24670043, 2014). "Recently, the S100A8/A9 heterocomplex was identified as a regulator of cell cycle progression and cell proliferation in cancer cell lines originating from the head and neck region." (PMID 24885002, 2014). "This chromosome region as well as S100A8/A9 TLR4 and RAGE receptors, has been associated with cancer development and metastasis." (PMID 24670043, 2014). "Little is known, however, about the intracellular roles of S100A8/A9 and how the protein complex regulates biological functions in cancer cells." (PMID 23874958, 2013). "TNF-alpha increases CXCL1 and CXCL2 expression in cancer cells and amplifies the CXCL1/2 S100A8/9 loop, which causes chemoresistance." (PMID 25562519, 2013). "Cancer cells overexpressing CXCL1 and CXCL2 attract CD11b(+)Gr1(+) myeloid cells into the tumor and produce chemokines including S100A8/9 that enhance cancer cell survival." (PMID 25562519, 2013).
cancer (continued). "In particular, S100A8 and S100A9 are the focus of intense research, as they are associated with several inflammatory diseases and cancer." (PMID 23626736, 2013). "In cancer, extracellular S100A8/A9, typically released from the cytoplasm of infiltrating polymorphonuclear leukocytes and macrophages, is associated with inflammation and progression of the disease." (PMID 23874958, 2013). "S100A8 and S100A9 are Ca2+-binding proteins that are associated with acute and chronic inflammation and cancer." (PMID 23626736, 2013). "Further studies into the fate of the G2/M arrested carcinoma cells will be essential to explain how S100A8/A9 exerts long-term effects on cell division." (PMID 23874958, 2013). "Although the loss of both G1/S and G2/M checkpoints are required for increased growth and proliferation in carcinomas, S100A8/A9-dependent induction of the G2/M checkpoint contributed significantly to the suppression of mitotic activity and growth of KB cells." (PMID 23874958, 2013). "To test the regulatory role of S100A8/A9 by rescue in S100A8/A9-negative carcinoma cells, we stably transfected KB cells to express S100A8/A9 protein complex." (PMID 23874958, 2013). "Since knockdown of S100A8/A9 in TR146 cells resulted in marked increase in growth and colony formation in soft agar, our data, therefore, strongly suggests a concentration-dependent effect of S100A8/A9 on carcinoma cell growth and clonogenicity." (PMID 23874958, 2013). "Concurrently, these carcinomas displayed strong co-overexpression of all five S100A8—NF-κB signaling markers." (PMID 20857495, 2011). "Other members of the S100 family, including S100A8, identified in cohort 2, are overexpressed in common cancers." (PMID 18211683, 2008). "Resolving the molecular mechanisms mediated by S100A8/A9 may reveal opportunities for designing novel cancer therapeutics." (PMID 39796176, 2025). "Indeed, single-cell RNA-Seq demonstrated that ATG9A KO in cancer cells promoted macrophage activation towards a cytotoxic phenotype, characterized by markers such as Inos, S100a8, Lcn2, and Cox-2." (PMID 40595560, 2025). "While functions and interactions of individual DAMPs have not been comprehensively characterized, in general HMGB1 and HSP70 reflect the degree of surgical injury or tissue damage, while increased S100A8/9 and S100A12 are associated with morbidity and mortality and cancer progression." (PMID 38468349, 2024). "S100A8 could exhibit effects in inflammation, immune response, and cancer development, but its biological functions are complex." (PMID 38361783, 2024). "A total of 735 cancer patients enrolled in 5 studies indicated a negative association between the expression of S100A8 and poor disease-free survival (DFS)." (PMID 38361783, 2024). "This provided new insights and proof that Sec C could serve as a promising anti-cancer prodrug and S100A8 could be a new drug target as well as a biomarker for cancer treatment and diagnosis." (PMID 38607060, 2024). "Previously published works into the role of S100A8, S100A9 or heterodimer S100A8/A9 in cancer." (PMID 39497822, 2024). "Furthermore, reprogramming the immune landscape with a single gene in non-cancer cells identified S100A8 as a regulator of an immune suppressive T and myeloid cell subtype." (PMID 38449858, 2024). "Thus, multivalent S100A8 inhibitory peptides would provide new pharmaceutical options for aggressive cancers." (PMID 36932197, 2023). "Although many studies have focused on the relationship and effects of TLR4 and S100A8/A9 in cancer, the mechanisms that could be developed as drug targets are not well-reported, and research in this area should be constantly strengthened." (PMID 37701037, 2023). "All cancer cell lines showed low levels of S100A8 transcript (mean Ct = 12.79 +/− 1.16)." (PMID 37627239, 2023). "Of tumors with ≥ 10% S100A8 + cancer cells 22/31 (71%) were Ki67 high." (PMID 37450087, 2023).